SMO (smoothened, frizzled class receptor)
Diseases named in the same sentence as SMO in open-access papers (continued):
Sharing a sentence is not in itself a finding about the gene and the disease.
hepatocellular carcinoma (13 papers, 2012 to 2025). A malignant tumor that arises from hepatocytes. "In hepatocellular carcinoma (HCC) patients, SMO mutation at the C-terminal lysine (K575M) involves the binding between PTCH and SMO to alleviate SMO from PTCH suppression to activate the downstream signaling." (PMID 31979397, 2020). "Here, results of stemness-related marker detection, sphere formation assays, and flow cytometry indicated that the down-regulation of SMO reversed the impact of HMGCR on the self-renewal ability of hepatoma cells." (PMID 39022130, 2024). "SHH/SMO signaling pathway activates in cancer stem cells (CD133+) of the mouse hepatoma cell line Hepa1-6." (PMID 32962123, 2020). "Others found a mutation in the C-terminal lysine (K575M) that allows for SMO to act independently of PTCH1 as it is unable to bind to and inhibit SMO, leading to uncontrolled signalling and expression of stem cell renewal genes in hepatocellular carcinoma cells (HCC)." (PMID 38920995, 2024). "Overexpression of SASH1 in hepatocellular carcinoma cells was found to inhibit SHH, SMO, PTC, and GLI1 expression, thereby reducing proliferation, migration/invasion, and EMT progression." (PMID 38498906, 2024). "In hepatocellular carcinoma, MIRLET7BHG promotes hepatocellular carcinoma progression by activating hepatic stellate cells through exosomal SMO to trigger the Hedgehog pathway." (PMID 35846147, 2022). "The diminished expression of SMO and its downstream Gli by THL further revealed its potential role on the eradication of hepatoma CSCs." (PMID 23097677, 2012). "In addition, THL dose-dependently inhibited the expression of important stemness genes such as the putative hepatoma stem cell marker CD133, as well as the Hedgehog signaling pathways components SMO and Gli." (PMID 23097677, 2012). "After sorting and subsequent culture, the SP cells from Huh7 hepatoma cells appear to have higher clonogenicity and mRNA expressions of stemness genes such as SMO, ABCG2, CD133, β-catenin, and Oct-4 than those of non-SP cells." (PMID 23097677, 2012).
colorectal cancer (12 papers, 2009 to 2025). A primary or metastatic malignant neoplasm that affects the colon or rectum. "In this study, we have determined that miR-338-3p inhibits cellular proliferation in GBM cell lines, mirroring the results of a similar analysis done on the role of miR-338-3p in colorectal carcinoma implicating loss of SMO inhibition." (PMID 28493990, 2017). "Taken together, these findings strongly suggest an important role of the intact Shh-SMO-GLI axis in promoting colorectal cancer tumorigenesis." (PMID 34572373, 2021). "For instance, functional SMO is required for the expression of GLI3 in colorectal carcinoma cell lines, and promoter methylation of SMO led to decreased GLI3 expression." (PMID 34572373, 2021). "Notably, it appeared that the expression of SMO was silenced in colorectal cancer cell lines harboring BRAFV600E." (PMID 20027224, 2009). "It has been demonstrated that elevated expression of SMO might contribute to colorectal tumorigenesis through activation of the Wnt signaling pathway in a mouse model and colorectal cancer cell lines." (PMID 20027224, 2009). "Conversely, treating colorectal cancer cells with demethylating agents 5-aza-20—deoxycytidine (5aza-dC) and TSA restored both SMO and GLI3 expression." (PMID 34572373, 2021). "Furthermore, the GLI3-mediated tumorigenesis in several colorectal cancer cell lines, such as LOVO, HT29, and SW480 cells, were found to be dependent on active SMO and Shh signals." (PMID 34572373, 2021). "First, our studies explained why SMO antagonists did not work in colorectal cancer treatment in previous clinical trials." (PMID 28413604, 2017). "This implies that the SMO antagonists, such as vismodegib, will not be effective in sensitizing colorectal cancer cells to chemotherapy, which was shown in the previous clinical trial." (PMID 28413604, 2017). "However, a SMO inhibitor, Vismodegib, did not extend progression-free survival in colorectal cancer patients." (PMID 29642386, 2018).
prostate carcinoma (12 papers, 2004 to 2024). A carcinoma that arises from epithelial cells of the prostate gland. "Additionally, in a low-androgen environment, both cyclopamine and siRNA directed against SMO caused downregulation of androgen-regulated genes in prostate cancer cells while administration of exogenous GLI1 allowed cell growth in an androgen-deficient medium." (PMID 26426053, 2015). "From a therapeutic point of view, a relevant finding of this study is that DAX1 activation and Hh signaling inhibition at the level of SMO act synergistically to decrease prostate cancer cell proliferation." (PMID 37504255, 2023). "Erismodegib (LDE-225, sonidegib), another SMO antagonist, influences cancer stem cell activity and decreases the invasiveness of glioblastoma, renal-cell cancer and prostate cancer." (PMID 32962123, 2020). "For instance, co-administration of the SMO inhibitor SANT-1 with the MEK1 inhibitor PD325901 in prostate cancer cells characterized by hyperactivation of MAPK signaling, has been shown to reduce prostate cancer cell growth more than either single agent alone." (PMID 31244888, 2019). "Vismodegib has been trialed in a variety of cancers, including pancreatic, ovarian cancer, breast and prostate cancers, and other SMO inhibitors are emerging such as sonidegib and BMS-833923." (PMID 29423837, 2018). "Our data demonstrate that targeting Hh signaling at the level of the GLI transcription factors is more effective than targeting it at the level of SMO in prostate cancer, as demonstrated using the GANT61 and GDC-0449 inhibitors respectively." (PMID 27713179, 2016). "Is SMO the optimal target to abrogate Hh signaling leading to the pleiotropic effects promoting prostate cancer growth?" (PMID 26426053, 2015). "With a specific SMO antagonist, cyclopamine, it will be possible in the future to treat prostate cancers, which have over-expressed sonic hedgehog." (PMID 15482598, 2004). "In this study, we evaluated the combination of two Hh inhibitors, the SMO inhibitor GDC-0449 and the GLI inhibitor GANT61 with radiotherapy in different prostate cancer (PCa) models." (PMID 27713179, 2016). "Indeed, targeting Hh signaling at the SMO level, with an SMO antagonist, and at the GLI1 level, with DAX1 activation, should result in a more potent inhibition of prostate cancer growth." (PMID 37504255, 2023). "Several clinical studies showed that the downregulation of intratumoral GLI1 levels did not correlate with tumor response in pancreatic and prostate cancer patients treated with SMO inhibitors." (PMID 34572373, 2021).
leukemia (11 papers, 2010 to 2024). A malignant (clonal) hematologic disorder, involving hematopoietic stem cells and characterized by the presence of primitive or atypical myeloid or lymphoid cells in the bone marrow and the blood. "The transmembrane protein smoothened (SMO), an essential regulator of Hh signal transduction, is highly expressed in CD34+ leukemia cells and can activate downstream glioma-associated oncoprotein (GLI) transcription factors to maintain the dormancy and chemoresistance of LSCs." (PMID 35865470, 2022). "Interestingly, similar to HL60/RX cells, HL60/ADR cells, a drug-resistant leukemia cell line, also showed significant radiation resistance and high levels of SMO and Gli-1." (PMID 27105509, 2016). "In these systems, LSC burden decreased commensurate with GLI2 and cell cycle regulatory gene repression and while GLI2 overexpression enhances dormant human leukemia stem cell generation, selective inhibition of SMO abrogates it and sensitizes them to tyrosine kinase inhibitors." (PMID 25889765, 2015). "Overall, our results inform the development of a clinically tractable strategy for obviating therapeutic resistance by selective SMO inhibitor targeting of dormant leukemia stem cells alone or in combination with standard of care in advanced hematologic malignancies." (PMID 25889765, 2015). "The Hedgehog signaling pathway is required to maintain the leukemic stem cell population; therefore, glasdegib binding and SMO inhibition reduce AML levels of GLI1 and AML leukemia initiation potential." (PMID 39001536, 2024). "Preclinical studies found that PF-913, an inhibitor of SMO, can decrease the proportion of CD34+ leukemia cells, induce dormant LSCs into the cell cycle, reduce leukemia initiation, and exert synergistic effects with cytarabine (AraC)." (PMID 35865470, 2022). "In fact, it has been reported that the SMO inhibitor cyclopamine and the WNT inhibitor quercetin suppressed the growth of leukemia cells." (PMID 35908024, 2022). "Our work addresses the role of smoothened (SMO) activation of its downstream hedgehog pathway transcriptional activator, GLI2, in human myeloid leukemia progression, leukemia stem cell self-renewal and dormancy." (PMID 25889765, 2015). "Interestingly, although Glasdegib is a SMO-inhibitor, its effects downstream of its SMO-inhibitory action include GLI2 inhibition which abrogates leukemia stem cell dormancy." (PMID 34540690, 2021). "Furthermore, BM from the diseased mice was retransplanted into secondary hosts and no mice receiving SMO−/−/BCR-ABL1/GFP+ cells developed leukemia, unlike controls, who developed leukemia within two months." (PMID 36986819, 2023).
chronic myeloid leukemia (10 papers, 2015 to 2023). "The HH pathway, and in particular the protein Smoothened (SMO), has been shown to be essential for regulating stem cell fate in chronic myeloid leukemia (CML)." (PMID 36986819, 2023). "In chronic myelogenous leukemia (CML), the loss of SMO impaired the self-renewal capacity of the hematopoietic stem cells and hindered the initiation of CML by the oncoprotein: BCR-ABL1." (PMID 36359888, 2022). "Regarding Hedgehog signaling, the expression of SMO (a G protein–coupled receptor protein) is inversely related to the CSCs activity in chronic myeloid leukemia in a way that SMO knockout leads to CSCs enhancement and disease progression." (PMID 35505363, 2022). "The top scoring candidates included Nilotinib and Imatinib, two protein kinase inhibitors used to treat chronic myelogenous leukemia; their docking scores were comparable to those of the known SMO modulators Vismodegib and SAG." (PMID 31539380, 2019). "The upregulated miR-326 was revealed to decrease SMO expression, resulting in an elevated rate of apoptosis in chronic myeloid leukemia (CML) cells, which could be beneficial in eradicating CD34+ CML stem cells." (PMID 34959397, 2021). "Besides, SMO inhibitors are combined with BCR-ABL modulators for chronic myeloid leukemia (CML) treatment." (PMID 30081498, 2018). "HH78 was shown to displace the fluorescent SMO antagonist BODIPY-cyclopamine using U2OS cells overexpressing human SMO and to overcome vismodegib resistance in chronic myeloid leukemia cells." (PMID 30558232, 2018). "HhP genes SHH, SMO, and GLI-1 are upregulated in chronic myeloid leukemia (CML) patients and are further elevated in blast crisis as compared to chronic-phase CML." (PMID 26483188, 2015).
liver fibrosis (10 papers, 2016 to 2026). "Inhibition of the Hh hub with vismodegib, a SMO antagonist, also stimulated the regression of both hepatic fibrosis and HCC." (PMID 36811777, 2023). "In the CCl4‐induced liver fibrosis model in mice, IHC staining showed that in the vehicle group there was minimal expression of SMO and GLI1 in normal liver tissues, but increased expression in the CCl4 group." (PMID 31328391, 2019). "We demonstrate that MEG3 inhibits Hh-mediated EMT, at least in part, through interacting with SMO, which is a novel mechanism in regulation of liver fibrosis." (PMID 30282972, 2018). "Taken together, our results suggest an antifibrotic role of MEG3 in liver fibrosis and this is a first report to show MEG3-mediated EMT process in liver fibrosis via SMO protein." (PMID 30282972, 2018). "In conclusion, we demonstrate that MEG3 inhibits Hh-mediated EMT process in liver fibrosis via SMO protein and miR-212." (PMID 30282972, 2018). "This study provides novel evidence that plant-derived miR-55—originating from the traditional Chinese formula Ge Xia Zhu Yu Decoction—can be orally delivered and modulates the CK2α/SMO/Gli1 signaling axis, significantly ameliorating MAFLD-associated liver fibrosis." (PMID 41596397, 2026). "As the data obtained from the in vitro experiments indicated that TB4, acting via SMO and GLI2, was critical to the fate of HSCs, we examined the in vivo effect of TB4 on hepatic fibrosis in mice overexpressing the Tb4 gene (Tb4-Tg)." (PMID 28630423, 2017). "Given the importance of Hh signaling in mediating T cell development and cytotoxic functions, and its enrichment as leading GSEA hit, we confirmed differential RNA expression in CD8 T cells in disparate liver fibrosis severities in HCV infection by qPCR analysis of PTCH1, SMO, and GLI1 mRNA." (PMID 38887299, 2024). "Meanwhile, in liver fibrosis, the activated HSCs induced by TGF-β1 are capable of producing Hh ligands that bind to their patched receptor, releasing smoothened transmembrane protein (SMO) which stimulates the activation and nuclear translocation of the Gli transcription factors." (PMID 36811777, 2023).
ovarian carcinoma (9 papers, 2009 to 2023). A malignant neoplasm originating from the surface ovarian epithelium. "Similar results were observed in ciliated SKOV3 ovarian cancer cells that enrich SMO in response to SAG stimulation but fail to activate GLI1." (PMID 37830570, 2023). "This is consistent with disappointing results of the SMO inhibitor vismodegib in ovarian cancer patients." (PMID 33947352, 2021). "Selective inhibition or knockdown of SMO and other Hedgehog downstream effectors (e.g. Gli1) increased cDDP sensitivity in ovarian cancer cell cultures and xenografts." (PMID 26910918, 2017). "In addition to SHH, we also detected expression of SMO and Su(Fu) in 17 ovarian cancers." (PMID 19943941, 2009). "Our studies further reveal the putative upstream involvement of PDGF-BB/PDGFR-β potentiating CSC/MSC Hedgehog signaling through PTCH, SMO and GLI1, all documented to result in platinum resistance of ovarian cancer." (PMID 32726910, 2020). "Most tumors with elevated expression of Gli1 and PTCH1 had no expression of SMO, suggesting that SMO expression was not responsible for hedgehog signaling activation in ovarian cancer." (PMID 19943941, 2009).
osteosarcoma (8 papers, 2010 to 2025). A usually aggressive malignant bone-forming mesenchymal neoplasm, predominantly affecting adolescents and young adults. "In osteosarcoma, overexpression of Hedgehog ligands and receptors, as well as mutations in pathway components, such as SMO and PTCH1, can result in increased Hedgehog signaling activity, promoting tumor growth and metastasis." (PMID 38428404, 2024). "Expression of Hh pathway signalling components and transcriptional target genes such as SHH, IHH, PTCH1, SMO, and GLI2 is also associated with high-grade osteosarcoma and poor outcomes." (PMID 40983796, 2025). "We previously reported that inhibition of SMO or GLI prevents osteosarcoma growth in vitro and in vivo." (PMID 23861973, 2013). "Inhibition of the Hedgehog pathway by knockdown of SMO or GLI2 prevents osteosarcoma growth in vitro and in vivo." (PMID 23861973, 2013). "SMO has been identified as a potential drug target in osteosarcoma, as its inhibitor cyclopamine promotes G1 arrests and represses expression of cyclin D1, cyclin E1, SKP2, and pRb." (PMID 23251412, 2012). "In agreement with their findings, our results showed that inhibition of SMO by cyclopamine or SMO shRNA is efficient in suppressing tumourigenic properties of osteosarcoma cells both in vitro and in vivo." (PMID 20067614, 2010). "Inhibition of SMO by cyclopamine, a specific inhibitor of SMO, slowed the growth of osteosarcoma in vitro." (PMID 20067614, 2010). "Real-time PCR revealed that 9 of 9 human biopsy specimens of osteosarcoma increased SMO 1.44- to 55.5-fold." (PMID 20067614, 2010). "The functional importance of Hh signalling in osteosarcoma is highlighted in preclinical studies in which pathway activation is inhibited at the level of SMO or GLI, leading to reduced osteosarcoma cell growth in vitro and tumour growth in in vivo xenograft models." (PMID 40983796, 2025). "Based on our data from mouse bone development and osteosarcoma, we hypothesized that inhibition of SMO signaling in established osteosarcoma would result in tumor growth arrest and differentiation." (PMID 37845394, 2023). "Furthermore, this result provides a firm genetic basis for testing SMO antagonists as potential therapeutics in osteosarcoma." (PMID 37845394, 2023). "Our findings suggest that inactivation of SMO may be an attractive target for the treatment of patients with osteosarcoma." (PMID 20067614, 2010). "Although, there is a possibility that anti-osteosarcoma effect by cyclopamine was partially dependent to the effect on bone marrow stromal cell, anti-tumor effect of SMO shRNA revealed that inactivation of SMO directly inhibits osteosarcoma proliferation in vitro and in vivo." (PMID 20067614, 2010). "We next examined SMO expression in osteosarcoma patient' biopsy specimens." (PMID 20067614, 2010). "MTT assay revealed that knock-down of SMO prevented osteosarcoma growth in vitro." (PMID 20067614, 2010). "Further examination might be needed the relationship between SMO inhibition and Wnt-β-catenin signaling in osteosarcoma." (PMID 20067614, 2010).